STAT3 (signal transducer and activator of transcription 3)
Diseases named in the same sentence as STAT3 in open-access papers (continued):
Sharing a sentence is not in itself a finding about the gene and the disease.
tumor (continued). "In recent years, the JAK/STAT3 signaling pathway has been extensively studied, and researchers have proven that inappropriate activation of JAK/STAT3 in OS is always linked to physiological events such as defective tumor cell migration, invasiveness, metastasis, and vascular neogenesis." (PMID 37441462, 2023). "We confirmed that the phosphorylation levels of STAT3 in primary tumor tissues from mice injected with wild-type TMEM25-encoded AAV were significantly lower than those from mice injected with control AAV, or TMEM25-R326W or TMEM25-L338F encoded AAV by immunoblotting assay." (PMID 37095176, 2023). "Additionally, another study suggested that M2 tumor-associated macrophages promote tumor growth via the NF-κB/IL-6/STAT3 signaling pathway." (PMID 37759870, 2023). "Notably, in non-tumor tissue samples, the levels of pSTAT3 and STAT3 were lower in WT as compared with Stat2-deficient ApcMin/+ mice." (PMID 38001683, 2023). "A recognized transcription factor called STAT3 has been linked to tumours development." (PMID 37784183, 2023). "STAT3 is involved in the regulation of cell differentiation, proliferation, and survival in various malignancies and is associated with angiogenesis and immune dysfunction in tumor development." (PMID 37990309, 2023). "Interestingly, recent work in multiple mouse tumor models links necroptotic signaling to the activation of IL-6 and STAT3 while apoptotic signaling was linked to STAT5 activation, matching gene expression and cell death patterns in our models." (PMID 37819938, 2023). "Moreover, it was discovered that blocking JAK/STAT3 signaling caused significant reductions of CSC sphere formation in the transwell cocultures seeded with PDX tumor stromal cells in comparison with the vehicle treatment." (PMID 36982542, 2023). "As IL-6/gp130/STAT3 activation is associated with immunosuppressive TAMCs, including tumor-associated macrophages, we examined whether SC144 can influence M1/M2 polarization of macrophages in vitro." (PMID 37553327, 2023). "Interestingly, ID1 expression leads to IL-6 production, activating STAT3, which is known to drive tumor associated macrophages toward an immunosuppressive phenotype, also promoting angiogenesis, invasion and epithelial-mesenchymal transition (EMT)." (PMID 38028629, 2023). "CAFs can deposit and remodel the ECM and increase β1 integrin and signal transducer and activator of transcription 3 (STAT3) signal transduction, which leads to fibrosis and increased tissue tension, further causing vascular dysfunction and hypoxic tumor microenvironment." (PMID 35515122, 2022). "Not only do NFκB and STAT3 directly drive tumor cell biology, but they have also been implicated in the programming of suppressive immune cells, which may in turn drive failure of both endogenous immunity and immunotherapeutics." (PMID 35327456, 2022). "STAT3 was associated with tumor progression and invasive aptitude." (PMID 35409080, 2022). "Further, STAT3 phosphorylation is significantly associated with increased tumor progression." (PMID 36313702, 2022). "Moreover, elevated STAT3 activity in tumor-associated immune cells leads to an immunosuppressive microenvironment, further promoting tumor progression." (PMID 36324587, 2022). "Moreover, various lncRNAs were demonstrated to induce the STAT3 gene expression and were downregulated in cancer tissues, which were associated with the tumor progression and poor prognosis." (PMID 35356799, 2022). "Depending on the mutational profile of the tumor, STAT3 could play a dual tumor-suppressive or oncogenic role." (PMID 35158868, 2022). "Reports suggest that tumor aggression is associated with the activation of STAT3." (PMID 35401182, 2022).
tumor (continued). "The IL-6/STAT3 pathway activation has been implicated in microbiome-induced tumor progression." (PMID 36186905, 2022). "STAT3 promotes tumor growth, invasion, and tumor-associated macrophage proliferation." (PMID 35585990, 2022). "Therefore, our findings revealed that apoptosis in “inflammation–atypical hyperplasia–cancer” process was correlated with IL-6/STAT3 signaling pathway in CRC-associated tumor tissues." (PMID 35946886, 2022). "In addition, artesunate, another ART derivative, enables tumor-associated monocytes to repolarize tumoricidal inflammatory monocytes against leukemic cells by inhibition of JAK2/STAT3 pathway." (PMID 35785030, 2022). "In tumor tissues, STAT3 activation in B cells is positively associated with tumor angiogenesis." (PMID 36249034, 2022). "Moreover, the potential clinical relevance is underlined by recent observations from our group, showing that increased STAT3 activation in fibroblasts in human CRC at early tumor stages is associated with reduced overall survival." (PMID 35326623, 2022). "Recent investigations have elucidated the role of IL-13Rα2 as a tumor-associated antigen that mediates aberrant STAT3 signaling, driving increased expression of anti-apoptotic genes and, ultimately, promoting tumor progression by blocking cell death and mediating survival." (PMID 35631512, 2022). "STAT3 deficiency can reduce the tumor burden in AOM/DSS-treated mice." (PMID 35205671, 2022). "The NF-κB/IL-6/STAT3 signaling cascade was closely associated with the inflammatory response, which induced proliferation and remodeling of epithelial cells and then promoted tumor development." (PMID 35991881, 2022). "Importantly, both STAT3 and STAT5 can be cell type‐ or mutational context‐dependent oncoproteins or tumor suppressors, but we conclude that all three gene products, STAT3, STAT5A, and STAT5B, are oncogenes in L‐CTCL." (PMID 36341492, 2022). "In addition, key autophagy protein inhibition seems to play an important role in the protective effects of RT on tumor-induced muscle atrophy since it is directly associated with persistent IL-6 production and phosphorylation of STAT3." (PMID 35847939, 2022). "Indeed, STAT3 is a main oncogenic TF whose activation contributes to expression of target genes implicated in tumor cell proliferation, survival, tumor invasion, angiogenesis, metastasis, and immunosuppression." (PMID 35847174, 2022). "Importantly, our previous studies showed that the level of HIF-1α and the activities of NF-κB and STAT-3 were induced and associated with tumor development in RT-R-MDA-MB-231 cells compared to MDA-MB-231 cells." (PMID 36077661, 2022). "Additionally, STAT3/STAT5 activation has been found in tumor-associated NK cells (TANKs), and treatment with a STAT5 inhibitor called pimozide reduced the ability of endothelial cells to produce VEGF." (PMID 36419156, 2022). "In addition, our findings linked STAT3 activation in COL1+ CAFs with enhanced proliferation in tumor epithelial cells, suggesting paracrine and/or contact dependent molecular cross-talk." (PMID 35326623, 2022). "Evidence from different tumor entities suggested that the inhibition of STAT3-associated signaling could represent a suitable therapeutic approach." (PMID 35326623, 2022). "Knockdown of STAT3 brought a loss of tumor formation in immunodeficient mice." (PMID 36230984, 2022). "Moreover, STAT3 participates in tumor migration and invasion, and persistent activation of STAT3 in epithelial/tumor cells is linked to multiple human malignancies, including inflammation-associated cancer." (PMID 36014573, 2022). "IL6-induced STAT3 deregulation is associated with tumor progression in various cancers." (PMID 35264191, 2022). "Notably, PAK1 is also an upstream effector of STAT3 and NF-κB, associated with inflammation-associated malignancy, suggesting its role in inflammation-related tumor progression." (PMID 36012284, 2022).
tumor (continued). "Activation of STAT3 in tumor-associated fibroblasts promotes angiogenesis in CRC." (PMID 36286020, 2022). "Considering that FISS is regarded as a chronic inflammation-associated tumor with histological features that are similar to wound healing, the expression of STAT3 may be significant and plays an important role in tumorigenesis." (PMID 35836213, 2022). "High concentrations of IL-6 in the tumor microenvironment were identified as one of the main causes of cancer growth, and lactate plays an important role in the expression of IL-6 and the activation of the STAT3 signaling pathway." (PMID 36686771, 2022). "Furthermore, it is biologically (and therapeutically) relevant, as loss of STAT3 expression or transcriptional function in these human tumor models abrogates the malignant transformation of these cells." (PMID 34953855, 2022). "Stat3 target genes include Bcl-X and Bcl-2, both encoding anti-apoptotic proteins, and cooperation with c-Jun constitute yet another mechanism of interference with tumor cell apoptosis." (PMID 36376859, 2022). "Also, activating the epithelial-mesenchymal transition (EMT) program by inducing EMT-transcription factor (TF)s by TrkC/DJ-1/STAT3 signaling pathway is the direct cause of multiple tumor malignancies of HCC." (PMID 36202793, 2022). "Moreover, accumulating experimental results indicated that STAT3 is hyperactivated in both tumor cells and tumor-associated immune cells, which consolidates immunosuppression." (PMID 36080223, 2022). "Moreover, mS100a7a15 can recruit leukocytes and tumor-associated macrophages (TAM) via RAGE/Stat3 signaling and thus promote tumor progression and metastasis." (PMID 36235175, 2022). "STAT3 activation has been associated with tumor survival, growth and progression." (PMID 35265066, 2022). "STAT3 phosphorylation and activation in reactive astrocytes has also been associated with tumor metastasis to brain, possibly by contributing to a microenvironment that attracts tumor cells from distal locations." (PMID 35316217, 2022). "The expression of STAT3 was negatively associated with all tumor types." (PMID 36176415, 2022). "Recent studies show that STAT3 may serve as a critical oncogenic factor and is associated with tumor cell proliferation, invasion, migration, therapy resistance, and poor prognosis in certain types of cancer." (PMID 36225196, 2022). "Many tumor-producing factors that are critical for tumor growth and immunosuppression, such as IL-6, IL-10 and VEGF, activate STAT3 to create an efficient “feedforward” mechanism to ensure increased STAT3 activity both in tumor cells and in tumor-associated immune cells." (PMID 34875483, 2022). "CDDO-Me has shown efficacy in multiple tumor models and has been shown to regulate activation of multiple signaling pathways implicated in carcinogenesis and cancer progression, including Nrf2, NFκB, and STAT3." (PMID 35265066, 2022). "STAT3 expression in tumor-associated immune cells was also exceptionally strong." (PMID 36561336, 2022). "In addition, tumor-associated B cells expressing STAT3 are reported to produce vascular endothelial growth factor in the tumor site, inducing angiogenesis and further tumor progression." (PMID 35893814, 2022). "In addition, activation of STAT3 helped the immunosuppressive polarization of tumor-associated macrophages, which contributed to the tumor development." (PMID 36231093, 2022). "Furthermore, SND1 (chromosome 7) exerts a cis-effect on protein level and was associated with the activation of STAT3, which was relevant to tumor proliferation." (PMID 35659036, 2022).
tumor (continued). "Through GSEA enrichment analysis, we also observed that low PAQR5 gene expression was associated with upregulation of STAT3 targeting, downregulation of tumor metastasis, upregulation of tumor formation, poorer tumor differentiation, and downregulation of the NRAS signaling pathway." (PMID 36119517, 2022). "It was reported that changes in MSCs in tumor microenvironment may associate with Stat3, so Stat3 was selected as a biomarker to study the cause of co-cultured MSCs transformation." (PMID 36295083, 2022). "In addition to its effects on tumor-associated immune cells, the enhanced activity of STAT3 via IL-6 family cytokines on CAFs is of great interest regarding its indirect tumor-promoting effects." (PMID 36010693, 2022). "However, STAT3 deficiency promoted late tumor progression and led to the formation of invasive and metastatic carcinomas via the enhancement of carcinoembryonic antigen-related cellular adhesion molecule 1, which is involved in intercellular adhesion." (PMID 36010693, 2022). "In addition, in a mouse transplant model, a loss of STAT3 signaling in the hematopoietic compartment facilitated the recruitment of tumor-infiltrating effector T cells and attenuated the infiltration of Treg cells." (PMID 36010693, 2022). "In addition, miR-31 regulates cross-talk between NF-κB and STAT3, which was associated with the progression of late-stage tumour development in a murine model of CRC." (PMID 34716428, 2022). "STAT3 has been shown to be a signaling hub in tumor cells as well as tumor–associated immune cells." (PMID 34532286, 2021). "Furthermore, STAT3 has been determined to be associated with drug resistance; tumor growth was reduced and cisplatin-induced chemo-cytotoxicity was enhanced after silencing of STAT3 expression." (PMID 34948424, 2021). "Therefore, our study has identified a critical mechanism intrinsic to PARPi that promotes resistance to PARPi and induces immunosuppression during PARPi treatment by activating STAT3 in tumor cells and tumor-associated immune cells/fibroblasts." (PMID 34956861, 2021). "Recent studies unveiled that STAT3 activity could be inhibited by S-nitrosylation at Cys259 in tumor-associated immune cells." (PMID 33925645, 2021). "The STAT3 signaling pathway is associated with tumor growth and reduction of T cell infiltration." (PMID 33407613, 2021). "After TYK2 activation, transcription factors such as signal transducer and activator of transcription 1 (STAT1) and STAT3, are dimerized and activated, thereby promoting the transcription of related genes and causing abnormal tumor cell proliferation and differentiation." (PMID 33731185, 2021). "Third, miR-1246 in tumor EVs activated STAT3 and Akt, causing drug resistance in ECs." (PMID 34226586, 2021). "Furthermore, the reduced tumor burden was linked to decreased Stat3 and NF-κB (RelA/p65) activation." (PMID 34680353, 2021). "However, in a transgenic mouse model of miR-17, overexpression of the microRNA is associated with reduced tumor migration and decreased STAT3 signaling." (PMID 34067095, 2021). "BBR or antibodies to IL-6 and IL-6R may also inhibit STAT3 activation by regulatory media of tumor-associated fibroblasts." (PMID 34885950, 2021). "Since our GSEA analysis found that CHRNA7 expression is associated with JAK2-STAT3 signaling in different cancers, we test the hypothesis that nicotine enhances tumor-initiating capacity by activating CHRNA7 and subsequently the JAK2/STAT3 pathway." (PMID 33603170, 2021). "Enterotoxigenic Bacteroides fragilis (ETBF) is a toxin-producing bacterium that can activate TH17-mediated colitis, with simultaneous colon-specific STAT3 activation and tumor stimulation in susceptible ApcMin (Multiple Intestinal Neoplasia) mice, which is reversed by IL-17 antibody blockade." (PMID 33823861, 2021).
tumor (continued). "Moreover, mutations in the SH2 and other regions of STAT3 are associated with increased tumor malignancy because they induce hyper-activation of the JAK/STAT pathway and resistance to dephosphorylation of STAT3." (PMID 33535185, 2021). "Preventing STAT3 activation could be an important therapeutic approach as STAT3 is one of the most known transcriptional factors associated with tumor progression." (PMID 34440697, 2021). "In keeping with these findings, more recently, it has been documented that chemotherapy activates the EZH2/STAT3 pathway in tumor cells, causing an increase in miR-378a-3p and miR-378d levels, in both cells and exosomes, which finally target the Notch pathway suppressor NUMB." (PMID 35582386, 2021). "Napabucasin inhibits the STAT3, which is associated with tumor stemness." (PMID 34326840, 2021). "Finally, IL-6 induces the development of immunosuppressive myeloid-derived suppressor cells (MDSCs) or tumor-associated macrophages (TAMs): their immunosuppressive functions occur through a STAT3-mediated mechanism." (PMID 34830209, 2021). "To analyze whether IL-17 may promote tumor growth via STAT3 during STAT1 deficiency, we evaluated STAT3 phosphorylation (pSTAT3) in colon tissue." (PMID 34299314, 2021). "The phenomenon might be caused by the activation of STAT3 and NF-kB signals, which have been reported to mediate drug resistance in several tumor types." (PMID 34657635, 2021). "Contrary to that, loss of STAT3 in PTEN-deficient mice enhanced tumor growth and metastasis." (PMID 34638338, 2021). "The constitutive activation of STAT3 can be controlled by various mechanisms, including the loss of negative regulators (PTPs, SOCS, and PIAS), the formation of positive feedback mechanisms in the tumor microenvironment, elevated activity of upstream kinases, and somatic mutations in the STAT3 gene." (PMID 34771643, 2021). "Moreover, IL-17 signaling in tumor cells and tumor-associated stromal cells can lead to IL-6 production and induce STAT3 activation." (PMID 34262562, 2021). "Furthermore, STAT3 inhibition by small molecules such as Galiellalactone causes apoptosis-mediated tumor regression in vitro and reduces regional and distal lymph nodes metastases in vivo." (PMID 34638338, 2021). "Moreover, activation of apoptosis inhibitors through the STAT3 pathway causes that B7-H6 induces proliferation in tumor cells." (PMID 34639059, 2021). "Interestingly, overexpression of STAT3-Flag in BCa cells not only restored their proliferation but also reversed the impairment of tumor sphere formation caused by BUB1 knockdown." (PMID 34852826, 2021). "Constitutive STAT3 activity can result in tumor progression toward the CRPC phenotype and may be associated with poor overall survival." (PMID 34830209, 2021). "However, further analyses of the patient samples revealed that CD109 expression significantly associated with increasingly phosphorylated STAT3 (p-STAT3, Tyr705) (P = 0.004) and higher number of Ki-67–positive, proliferating tumor cells (P = 0.027)." (PMID 33986188, 2021). "STAT3 hyperactivation in malignant cells, surrounding immune cells and cancer-associated fibroblasts, mediates inhibition of the innate and adaptive immunity of the tumor microenvironment, and, therefore, tumor evasion from the immune system." (PMID 34440220, 2021). "In addition, in RCC tumor cells and tumor-associated MDSC, sunitinib inhibits Stat3 activity leading to tumor cell apoptosis and promoting antitumor effect." (PMID 33854498, 2021). "Given that phosphorylated STAT3 could initiate transcription of target genes that are associated with tumor cell growth and apoptosis, the expression levels of STAT3 downstream targets were determined." (PMID 33753770, 2021).